CTCF (CCCTC-binding factor)
Diseases named in the same sentence as CTCF in open-access papers (continued):
Sharing a sentence is not in itself a finding about the gene and the disease.
breast carcinoma (continued). "The transcriptional control of Nm23-H1 by CTCF and EGR1 provides a mechanism for their ability to inhibit the metastatic process of breast cancer cells." (PMID 33436746, 2021). "NME1 can be transcriptionally regulated by a multitude of transcription factors, in particular by CTCF and EGR1, which potentially drive Nm23-H1 expression in breast cancer cells to promote a less metastatic phenotype." (PMID 33436746, 2021). "In non-invasive MCF7 breast cancer cells, MZF1 interacts with the CCCTC-binding factor (CTCF) via its acidic domain, which results in downregulation of the transcriptional activity of MZF1." (PMID 31963147, 2020). "We next sorted the RNASeq data of primary breast cancer patients based on RESTlow and RESThigh groups with 300 patients for each group and examined the expression patterns of TBP, CEBPB, REST, CTCF, RAD21 and SMC3 in addition to unsorted patient dataset." (PMID 30335837, 2018). "Additional support for these datasets was provided by another study that demonstrated that CTCF can interact with the KDM5B histone demethylase and increase its demethylation activity in breast cancer cell lines." (PMID 29682202, 2018). "Thus, CTCF might be an effective therapeutic target for the treatment of breast cancer." (PMID 29212169, 2017). "Our data suggests that CTCF not only provides boundaries for accessible and 'protected' transcriptional blocks, but may also influence the actual binding of ER to the chromatin, thereby modulating the estrogen-mediated gene expression changes observed in breast cancer cells." (PMID 22142239, 2011). "For a competition model to be feasible in breast cancer, levels of BORIS and CTCF mRNA and/or protein would have to be comparable." (PMID 20305816, 2010). "However, we could not detect any association between the intensity or pattern of expression of CTCF and tumour type and there was neither marked nor complete loss of expression in any specific type, suggesting that CTCF is not the likely TSG in breast cancer." (PMID 15354217, 2004). "Additionally, previous studies have shown that transcription factor CTCF binds to CLPTM1L promoter and regulates its expression in breast cancer cell." (PMID 40550808, 2025). "Diminished CTCF total protein was most evident in the input fraction but was also observed in soluble nuclear and chromatin-bound fractions for TGFβ-treated MCF10A cells and in EMT-positive breast cancer cell lines." (PMID 35008373, 2022). "Additionally, the modulation of the variable number of tandem repeat (VNTP) domain of the 5-HTT gene was regulated by CTCF, a multifunctional transcription factor that was previously found to regulate the tumor-suppressor activity of HOXA10 in breast cancer." (PMID 36430579, 2022). "Specifically, by binding to the CpG sites of miR-375, CTCF manages to silence its expression in estrogen receptor (ER) negative breast cancer cells." (PMID 33194751, 2020). "An overview of lesions of CTCF gene in various cancers studied by TCGA and in the METABRIC breast cancer study shows that the most common type of genetic lesions is mutations (1.97% of all samples examined), while amplifications and deep deletions were very rare (0.18% and 0.49%, respectively)." (PMID 30275357, 2018). "In addition, ENCODE Genome Institute of Singapore ChiA-PET data show interactions in our highlighted region for RNAPII and CTCF long-range binding in two different cell lines (K562 myelogenous leukaemia cells and MCF-7 breast cancer cells)." (PMID 26642925, 2015). "During the progression of breast carcinomas, perhaps, the non-malignant stage would sustain region D at the unmethylated state and thus facilitate the binding of CTCF to R4 region of RARRES1 promoter by which methylation at region P can be prevented." (PMID 22615834, 2012).
breast carcinoma (continued). "Notably, key transcription factors involved in ER+ breast cancer were highly enriched, including methylation-sensitive estrogen response elements (EREs) and ELF5 (ETS transcription factor family members), as well as architectural proteins CTCF and ZNF165." (PMID 38182927, 2024). "In breast cancer patients high levels of BORIS protein are detected in leukocytes, suggesting that BORIS can be used as an important biomarker for breast cancer progression and is a male system-specific protein having the same 11-zinc finger structure as that of CTCF." (PMID 37235839, 2023). "Collectively, these data indicate that CTCF and EGR1 act as transcription factors to drive Nm23-H1 expression in less metastatic breast cancer cells, whereas their lower expression in aggressive breast cancers may contribute to reduced levels of Nm23-H1." (PMID 33436746, 2021). "Moreover, in the breast cancer cell lines that we examined CTCF is no longer responsive to stress-induced protein downregulation nor enriched at SC-35 nuclear speckles." (PMID 33411704, 2021). "However, no significant change in the CTCF mRNA level was observed in breast cancer cell lines as compared with that in MCF-10A." (PMID 29212169, 2017). "Indeed, we found that promoters, CTCF sites, and enhancers could all exhibit characteristics of epigenetic activation in MCF7 breast cancer cells and in PC3 prostate cancer cells." (PMID 24916973, 2014). "Thus, aberrant BORIS expression is unlikely to compete with CTCF, even in the rare breast cancer cell line in which it is expressed." (PMID 20305816, 2010). "In conclusion, the current results show that CTCF, although it may play a role in breast carcinogenesis, is unlikely to be the TSG targeted by the 16q22.1 loss in breast cancer and thus another gene or genes at this region remain to be identified." (PMID 15354217, 2004). "Stress-induced downregulation of CTCF was also observed in spontaneously immortalized, non-tumorigenic human mammary epithelial MCF10A cells, although not in other human breast cancer cell lines that we tested." (PMID 33411704, 2021). "In conclusion, in most breast cancer cells, endogenous BORIS is unlikely to be expressed at sufficient levels to interfere with CTCF functions." (PMID 20305816, 2010).
prostate carcinoma (45 papers, 2009 to 2025). A carcinoma that arises from epithelial cells of the prostate gland. "CTCF presence was coupled with the prevalence of prostate cancer (PrCa) single nucleotide polymorphisms (SNPs) within the same EPIN clusters, suggesting functional implications in PrCa." (PMID 38057321, 2023). "Genome-wide association studies (GWAS) identified more than 100 prostate cancer risk loci, which were linked to long-range chromatin CTCF loop anchors which function to repress gene expression." (PMID 37627195, 2023). "In the low PES1 expression group, CTCF is a chromatin insulator and multifunctional transcription factor, and mutations in this gene are associated with invasive breast cancer, prostate cancer, HNSCC and nephroblastoma." (PMID 37076985, 2023). "For instance, in breast and prostate cancer, loss of CTCF copy number leads to hypermethylation of DNA at surrounding CTCF binding sites." (PMID 36612210, 2022). "Analyzing patient data sets from TCGA reveals frequent loss of the CTCF gene in breast and prostate cancer patients, correlating with hypermethylation of CpG islands and hypomethylation of other parts of the genome." (PMID 36589746, 2022). "In prostate cancer, the expression levels of CTCF showed strong association with the levels of proliferation marker Ki67, advanced pathological tumor stage, nodal metastasis, and early biochemical recurrence." (PMID 35966880, 2022). "In recent years, CTCF has been found to be mutated sporadically in diverse cancer types, such as leukemia, breast, uterine, and prostate cancers and is involved in inhibiting cancer cell growth and clonogenicity." (PMID 29212169, 2017). "In addition, CRISPR-mediated deletion of prostate cancer risk-associated CTCF loop anchors resulted in the de-repression of gene expression." (PMID 37627195, 2023). "It remains unknown if CTCF level is associated with organization of transcriptional condensates in prostate cancer cells, but studies in colorectal cancer cells showed a positive correlation." (PMID 35966880, 2022). "The results of our study show that CTCF expression is linked to poor outcome in prostate cancer." (PMID 31736271, 2020). "SNPs associated with CTCF sites are linked to prostate cancer risk." (PMID 31200487, 2019). "We next identify prostate cancer risk-associated CTCF sites involved in long-range chromatin loops." (PMID 30296942, 2018). "Moreover, mutation of LEF1 was found to be associated with somatic sebaceous tumors, whereas mutation of CTCF is associated with invasive breast cancers, prostate cancers, and Wilms' tumors." (PMID 26895224, 2016). "Deletion of two prostate cancer risk-associated CTCF anchor regions by CRISP-Cas9 resulted in highly elevated expression of genes within the loops, suggesting that disruption of TAD organization could alter gene expression and contribute to prostate tumorigenesis." (PMID 35966880, 2022). "However, genome‐wide association studies revealed single nucleotide polymorphisms in the CTCF region associated with prostate cancer risk and functional studies in cell lines demonstrated an impact of CTCF knockdown on prostate cell proliferation, migration, and invasion." (PMID 31736271, 2020). "However, in three prostate cancer cell lines, different environmental factors can cause the expression levels of the chimeric RNA to change, and these changes do inversely correlate with CTCF level, and/or its bindings to the insulators." (PMID 26938874, 2016). "In addition, motif analyses on accessible chromatin regions by FAIRE-seq identified motifs for a large range of other transcription factors previously linked to prostate cancer development and progression, including CTCF, SP1, FOS, and ETS domain family of transcription factors." (PMID 26412853, 2015). "CTCF transcriptionally represses miR - 127 - 3p by interacting with its promoter, activating the CTCF/miR - 127 - 3p/PSMB5 axis to promote prostate cancer bone metastasis." (PMID 40837012, 2025).
prostate carcinoma (continued). "Subsequently, cis-splicing between neighboring genes was also found to generate chimeric RNAs, such as the CTCF-sensitive cis-spliced fusion RNAs ADCK4-NUMBL in prostate cancer." (PMID 38165397, 2024). "CTCF silencing diminished the progression of prostate cancer via altering the FoxO signalling pathway." (PMID 38289488, 2024). "CTCF was also found to be a candidate prognostic biomarker for prostate cancer, and depletion of CTCF leads to reduced prostate cancer cell migration, invasion, and proliferation." (PMID 37627195, 2023). "Here, we show that MYC reshapes the chromatin architecture of prostate cancer (PCa) cells through interacting with CTCF protein." (PMID 36997534, 2023). "In this study, further exploration of the GRNs of prostate cancer identified key transcriptional regulatory factors, CTCF and SIN3A." (PMID 37627195, 2023). "MYC is a well characterized oncogenic transcription factor in prostate cancer, and CTCF is the main architectural protein of three-dimensional genome organization." (PMID 36997534, 2023). "Expression of the chromatin insulator, CTCF, which is involved in transcriptional regulation and chromatin loop formation, is overexpressed in prostate cancer relative to normal prostate tissue." (PMID 37627195, 2023). "In this study, we find that MYC rewires prostate cancer chromatin architecture by interacting with CTCF protein." (PMID 36997534, 2023). "Recent studies show the effect of the CTCF factor on some cancers like prostate cancer by regulating the FoxO pathway." (PMID 36251702, 2022). "In a follow-up study, the effect of CTCF on the organization of TAD was further explored in prostate cancer cells." (PMID 35966880, 2022). "CTCF sites differ among tumor types and result in tissue-specific methylation patterns with little overlap between breast and prostate cancers." (PMID 32503656, 2020). "We therefore explored the genome-wide chromatin effects of global CTCF depletion in prostate cancer cells to determine the role of CTCF in long-range epigenetically regulated domain organisation." (PMID 31911579, 2020). "This suggests that CTCF becomes upregulated during tumor development and/or progression in a relevant fraction of prostate cancers." (PMID 31736271, 2020). "The results of our study identify CTCF expression as a candidate biomarker for prognosis assessment in prostate cancer." (PMID 31736271, 2020). "To evaluate the clinical impact of CTCF in prostate cancer, we analyzed CTCF expression by immunohistochemistry on a tissue microarray containing 17 747 prostate cancers." (PMID 31736271, 2020). "To learn more on the impact of CTCF expression on the clinical course of prostate cancer, we took advantage of our large tissue microarray (TMA) resource including more than 17 000 prostate cancers." (PMID 31736271, 2020). "In summary, our study shows that CTCF expression is a prognostic unfavorable feature in prostate cancer, but CTCF is a candidate biomarker with low predictive power." (PMID 31736271, 2020). "CTCF staining was strongly linked to TMPRSS2:ERG rearrangement and ERG positivity in our set of prostate cancers (P < 0.0001)." (PMID 31736271, 2020). "Our immunohistochemical analysis revealed detectable CTCF staining in 61.5% of 12 555 analyzable prostate cancers." (PMID 31736271, 2020). "The present research focuses on the influence of CCCTC‐binding factor (CTCF) on prostate cancer (PC) via the regulation of the FoxO signalling pathway." (PMID 30873749, 2019). "We also performed ChIP-seq for modified histones and CTCF, NOMe-seq, and RNA-seq in normal and prostate cancer cells." (PMID 31515496, 2019). "A recent study used CRISPR/Cas9 to reveal long-range looping between disease-related genes and their regulatory elements that is mediated by the CCCTC-binding factor (CTCF) in prostate cancer." (PMID 30400943, 2018).
prostate carcinoma (continued). "CTCF was considered as a possible target for deletions of chromosomal regions of 16q22.1 that occur commonly in breast and prostate cancers." (PMID 29212169, 2017). "Additionally, the transcription factor MYC regulates prostate cancer-specific gene transcription by remodeling CTCF-mediated chromatin structure." (PMID 40475780, 2025). "In prostate cancer, CTCF interacts with other proteins to regulate gene expression." (PMID 38658701, 2024). "Interestingly, “Prostate cancer” pathway genes were enriched in both common and cell-type-specific CTCF loop anchors, which is consistent with the tissue origin of VCaP and 22Rv1 cells, suggesting CTCF looping is involved in tissue-specific gene regulation." (PMID 36997534, 2023). "While CTCF is a known chromatin insulator, which blocks enhancer function between TADs, it is unclear how CTCF reprograms the epigenetic landscape of prostate cancer cells to drive prostate cancer tumor progression, castration-resistance, and enzalutamide-resistance." (PMID 37627195, 2023). "The functional link between MYC and CTCF in prostate cancer remains to be investigated." (PMID 36997534, 2023). "Indeed, in prostate cancer cells, the boundaries established by CTCF showed more effective AR transcriptional regulation than in normal cells." (PMID 35966880, 2022). "CTCF knockdown in prostate cancer cells leads to hypermethylation at CTCF-binding sites." (PMID 34429148, 2021). "Besides, CTCF (CCCTC-binding factor) was validated to activate HOXA11-AS transcription in prostate cancer cells and consequently to facilitate cell proliferation and migration by targeting miR-518b/ACTN4." (PMID 34715856, 2021). "CTCF can affect the progression of prostate cancer by regulating the FoxO signaling pathway." (PMID 34692659, 2021). "Little is known about the clinical impact of CTCF expression in prostate cancer." (PMID 31736271, 2020). "It is, thus, tempting to speculate that prostate cancer patients with CTCF expression may benefit from novel therapies targeting telomere instability once they become available." (PMID 31736271, 2020). "Investigation of the function of other GWAS-identified CTCF sites involved in chromatin loops may reveal additional genes involved in the development or diagnosis of prostate cancer." (PMID 30296942, 2018). "To validate this hypothesis, we employed the CTCF-based 3D chromatin interaction data from two prostate cancer cell lines, 22Rv1 and VCaP, as well as the prostate epithelial cell line RWPE-1 to examine the spatial relationship among eCpG, eGene, and eSNP (“Methods”)." (PMID 38066556, 2023). "To further delineate the function of CTCF in PCa, we generated CTCF-mediated chromatin contact maps by HiChIP in VCaP and 22Rv1, two widely used PCa cell lines derived from a vertebral metastasis of a prostate cancer patient and a human prostatic carcinoma xenograft, respectively." (PMID 36997534, 2023). "Both CTCF and SIN3A were found to have low depmap dependency scores for multiple prostate cancer cell lines." (PMID 37627195, 2023). "An example of CTCF-loop-regulated gene is TMC5, which is transcriptionally suppressed by androgen stimulation in VCaP cells and has been reported to promote prostate cancer cell proliferation." (PMID 36997534, 2023). "Both CTCF and SIN3A were observed to have overexpression in prostate cancer compared to normal tissue." (PMID 37627195, 2023). "An exploration of the prostate cancer GRN revealed a subnetwork comprised of two chromatin constituents, CTCF and SIN3A." (PMID 37627195, 2023). "In particular, the results of our PCR-array suggested that CTCF suppresses the expression of RORB and TIMP3, which are genes that inhibit metastasis in prostate cancer and breast ductal cancer." (PMID 28977939, 2017).
prostate carcinoma (continued). "Further ChIP-seq analysis in prostate cancer cell lines indicated multiple positive signals in the EcoRI fragment BE8-9 (chr2: 85778503–86781283) including H3K4me1 and FOXA1 in LNCaP; CTCF and FOXA1 in VCaP, and RAD21 in NCIH660." (PMID 26979803, 2016). "Normal prostate tissue showed negative to low CTCF expression, while in prostate cancers, CTCF expression was seen in 7726 of our 12 555 (61.5%) tumors and was considered low in 44.6% and high in 17% of cancers." (PMID 31736271, 2020). "Taken together with previous studies, our work suggests that binding of CTCF to rs12144978 may, via its repressive role on KCCN3 expression, play a protective role regarding human prostate cancer." (PMID 30296942, 2018). "At this moment, the role of CTCF in regulating global cis-SAGe events in clinical prostate cancer is not clear." (PMID 25658338, 2015). "Finally, we showed that genome-wide CTCF depletion had little effect on gene expression levels or active chromatin distribution across the adjacent LRES and LREA domains in the KLK gene locus in prostate cancer cells." (PMID 31911579, 2020).